FASN (fatty acid synthase)
Diseases named in the same sentence as FASN in open-access papers (continued):
Sharing a sentence is not in itself a finding about the gene and the disease.
breast cancer (continued). "Targeting enzymes involved in these metabolic pathways, such as FASN, has emerged as a promising therapeutic strategy in breast cancer treatment." (PMID 40733158, 2025). "In this study, resveratrol reduced intracellular fatty acid levels by inhibiting FASN activity and downregulating its expression across various breast cancer subtypes, including SK-BR-3, MCF-7, and MDA-MB-231 cells." (PMID 40733158, 2025). "Firstly, FASN demonstrates a considerably elevated level of expression in breast cancer tissue compared to normal breast tissue." (PMID 40002245, 2025). "Collectively, these findings support resveratrol as a promising anti-cancer candidate that induces apoptosis in diverse breast cancer subtypes via FASN inhibition." (PMID 40733158, 2025). "While the antitumor effects of resveratrol in breast cancer have been described, comparative analyses across molecular subtypes characterized by distinct FASN expression remain limited." (PMID 40733158, 2025). "Subsequent analysis of intracellular FASN enzymatic activity revealed a marked decrease in all three breast cancer cell lines following resveratrol exposure for 24 h." (PMID 40733158, 2025). "In breast cancer cells, hsa-miR-195 induces apoptosis by targeting genes such as Bcl-2 and FASN; however, aberrant activation of MYC can antagonize the pro-apoptotic effect of miR-195 by upregulating anti-apoptotic proteins like Bcl-xL." (PMID 41210882, 2025). "Among these, investigations into the role of FASN in modulating drug sensitivity in HER2-positive breast cancer have been particularly profound." (PMID 40303293, 2025). "It is well recognized that breast cancer versus normal cells increase FASN driven de novo FA synthesis." (PMID 40055794, 2025). "FASN levels are consistently higher in breast cancer compared to normal cells and breast tumor vs. normal tissue." (PMID 40055794, 2025). "In this study, we investigated alterations in lipid metabolism in ER + breast cancer cell lines with acquired resistance to common endocrine therapies and evaluated the efficacy of a clinically relevant fatty acid synthase (FASN) inhibitor." (PMID 40055794, 2025). "In breast cancer, small molecules such as pristane and its derivatives target the malonyl/acetyltransferase domain of fatty acid synthase (FASN), disrupting fatty acid‐mediated MHC‐II silencing and thereby promoting CD4+ T cell infiltration." (PMID 40673641, 2025). "Fatty acid synthase (FASN) is frequently overexpressed in human breast cancer and has emerged as a potential therapeutic target." (PMID 40733158, 2025). "Pharmacologic inhibition of fatty acid synthase has been shown to trigger apoptosis during the S phase in human breast cancer cells, with C75-induced disruptions in phospholipid synthesis." (PMID 40422212, 2025). "Resveratrol is a promising anti-cancer agent for different breast cancer subtypes with regard to cell apoptosis by inhibiting FASN." (PMID 40733158, 2025). "FASN is frequently overexpressed in breast cancer and correlates with poor prognosis, aggressive phenotype, and resistance to therapy." (PMID 40733158, 2025). "Our findings, consistent with previous reports, indicated a gradient of FASN expression across breast cancer cell lines, with SK-BR-3 exhibiting high levels, MCF-7 moderate, and MDA-MB-231 very low expression." (PMID 40733158, 2025). "For instance, inhibiting FASN sensitizes breast cancer cells to doxorubicin by disrupting lipid synthesis." (PMID 39456967, 2024). "CircZFAND6 acted as a ceRNA by sponging miR-647, resulting in increased FASN expression that promoted breast cancer proliferation and metastasis." (PMID 38408962, 2024). "Extending these observations, FASN expression negatively correlated with three derived measures of T-cell receptor (TCR) repertoire enrichment in both breast cancer and pan-cancer datasets (PCCs ranging from −0.014 to −0.06; FDR-adjusted p-values < 10−4)." (PMID 39349429, 2024).
breast cancer (continued). "Despite strong evidence supporting FASN as a promising target for breast cancer therapy, only a few compounds inhibiting FASN have entered clinical studies to date." (PMID 39834807, 2024). "In breast cancer, FA synthesis was reported to be heightened via the upregulation of several lipogenic enzymes, such as FASN and ACLY." (PMID 39351361, 2024). "A clinical investigation involving 24 breast cancer patients administered CLA orally at 7.5 g/day for 20 days revealed inhibition in the expression of fatty acid synthase (FASN) and lipoprotein lipase (LPL), indicating breast tumor growth suppression." (PMID 38592012, 2024). "As another crucial enzyme involved in DNL, FASN also contributes to breast cancer initiation, progression, and treatment resistance." (PMID 39834807, 2024). "This process, particularly the upregulation of fatty acid synthase (FASN), plays a crucial role in supporting the rapid growth and survival of cancer cells, including those in breast cancer." (PMID 39408832, 2024). "In HER2 positive breast cancer, adipogenesis plays a more significant role than other subtypes due to the upregulation of fatty acid synthase(FASN) transcription by the HER2 gene, leading to an increase in de novo fatty acid synthesis." (PMID 39333940, 2024). "It has been shown that the antitumoral activity of ORL is linked with its ability to block fatty acid synthase (FAS) activity, which subsequently inhibits the proliferation of Her2/neu breast cancer cells." (PMID 38256929, 2024). "FASN expression in breast cancer cells can be reduced by both the mTOR inhibitor rapamycin and MAPK pathway inhibition." (PMID 39791706, 2024). "Previous reports suggest that cacalol has an anti-breast cancer effect by inhibiting fatty acid synthase (FAS) at transcriptional and post-transcriptional levels and modulating the Akt-SREBP (sterol regulatory element-binding protein) pathways." (PMID 39329902, 2024). "Fatty acid synthase (FASN), a crucial enzyme involved in the synthesis of fatty acids, is associated with trastuzumab resistance in breast cancer." (PMID 38413011, 2024). "Curcumin, a natural fatty acid synthase inhibitor, inhibits the proliferation of tumor cells, induces apoptosis of tumor cells, and is widely used in the treatment of breast cancer, lung cancer, pancreatic cancer, and other tumors." (PMID 39070787, 2024). "FASN exhibits high expression in cancer stem cells, and its inhibition effectively suppresses the proliferation and survival of breast cancer cells." (PMID 39471412, 2024). "Taken together, we conclude that FASN regulates p65 expression and NF-κB activity in breast cancer cells." (PMID 38467328, 2024). "Among the 11 studies included in our analysis, three investigated the role of FASN in breast cancer adipogenesis and its impact on prognosis." (PMID 39333940, 2024). "Overexpression of FASN in breast cancer (BC) leads to chemoresistance, and improving chemotherapy-susceptibility can be achieved through targeted suppression of FASN." (PMID 38357546, 2024). "Compounds like resveratrol and curcumin have demonstrated efficacy in downregulating FASN expression and lipid synthesis, thereby reducing cell survival and promoting apoptosis in breast cancer cells." (PMID 39287822, 2024). "Recent studies have shown that breast tumors in the brain must adapt to the low lipid availability in the brain by increasing de novo fatty acid synthesis and targeting the enzyme fatty acid synthase (FASN) can block breast cancer growth in the brain." (PMID 38818373, 2024). "Previousreports have shown upregulation of FA synthase (FASN) in breast cancer, including LTED cells." (PMID 37497607, 2024). "Proteomics results showed that FASN was overexpressed in breast cancer cell lines with a multidrug resistant phenotype, the expression of which increased with the level of drug resistance." (PMID 38819674, 2024).
breast cancer (continued). "Inhibiting FASN in HER2-positive advanced breast cancer cells has reduced cancer growth in both preclinical and clinical studies." (PMID 39456967, 2024). "As a central regulator of lipid metabolism, FASN plays a critical role in the growth of tumors with lipogenic phenotypes, such as those of breast cancer, ovarian cancer, and hepatocellular carcinoma." (PMID 38953350, 2024). "Adipogenic enzymes, particularly fatty acid synthase (FASN), play a crucial role in the regulation of metabolic pathways in breast cancer adipogenesis." (PMID 39333940, 2024). "The inhibition of FASN in breast cancer stem cells has been shown to significantly reduce their self-renewal and growth capabilities, highlighting the enzyme’s essential role in maintaining the malignant phenotype of these cells." (PMID 39408832, 2024). "It was demonstrated that the selective inhibition of FASN attenuated the progression of prostate cancer, non-small-cell lung cancer, and metastasized breast cancer." (PMID 39273384, 2024). "Subsequently, these researchers extended their findings that EGCG attenuated EGFR 2 (HER2) or/and EGFR 3 (HER3)-induced FASN overexpression in breast cancer cells through suppressing PI3K/Akt signaling." (PMID 38348027, 2024). "Nonetheless, previous observations imply that FASN-mediated inhibition of the retinoblastoma (pRB) tumor suppressor pathway is the primary mechanism responsible for SKP2 induction in breast cancer cells." (PMID 39064589, 2024). "ORL inhibits angiogenesis (VEGF, MMP-9, and CXCR4/CXCL12) and fatty acid synthesis (ACLY, ACC, and FASN) genes and protein expression with the induction of apoptotic genes in different breast cancer cell lines." (PMID 38256929, 2024). "Overexpression of FASN has been reported in solid tumors and hematopoietic tumors, including non-small cell lung cancer, breast cancer, ovarian cancer, prostate cancer, and lymphoma 51, which is consistent with the results of our on-target analysis." (PMID 38164137, 2024). "Previous studies have shown fatty acid synthesis is elevated and critical for breast tumors growing in the brain and the enzyme responsible for de novo lipid synthesis, fatty acid synthase (FASN) is required for growth and survival of these tumors." (PMID 38818373, 2024). "Several studies have demonstrated a role for FASN in the resistance of HER2 over-expressing breast cancers to standard of care agents including cytotoxic chemotherapies and anti-HER2 therapies." (PMID 37779896, 2023). "Two metabolic enzymes, ACC and FASN, participating in fatty acid de novo synthesis, were also found to be abnormally up-regulated in breast cancer tissues." (PMID 37120513, 2023). "In recognition of this vulnerability, combination with a FASN inhibitor and trastuzumab sensitized trastuzumab-resistant breast cancer cell lines by downregulating HER2 expression." (PMID 37779896, 2023). "Previous studies reported that FASN played a vital role in breast cancer metastasis and progression." (PMID 37696831, 2023). "OST inhibits FASN expression in HER2-overexpressing breast cancer cells by regulating the Akt/mTOR pathway." (PMID 36674685, 2023). "Further, we explored the roles of ACC and FASN, two key enzymes in the fatty acid synthesis pathway, in the proliferation and metastasis of breast cancer cells." (PMID 37120513, 2023). "In this study, by performing spatially resolved MALDI-MSI and immunofluorescence analysis, we found that the expressions of palmitic acid, ACC, and FASN in breast cancer tissues all were significantly higher than those in normal tissues." (PMID 37120513, 2023). "Except for the retrieved topics, “lipid metabolism” (n = 272) and “breast cancer” (n = 175), the keywords that appeared most frequently were “expression” (n = 151), “fatty-acid synthase” (n = 78), “growth” (n = 72), “metabolism” (n = 67) and “cells“ (n = 66)." (PMID 37179822, 2023).
breast cancer (continued). "In the breast cancer cell model, Ruidas and colleagues have shown that quercetin down-regulates the expression level of both FASN and CPT1, as well as β-oxidation intensity and tumor growth in vivo." (PMID 38001865, 2023). "As a proof of principle, using only plasmid HDR template, we also tagged two proteins, GAPDH and FASN, in a breast cancer cell line MDA-MB468 with a FLAG tag." (PMID 37487103, 2023). "As examples, we tagged GAPDH and FASN in the breast cancer cell line MDA-MB468, although no further analysis was performed at this stage." (PMID 37487103, 2023). "ALA can also stabilize HIF-1 expression in MCF-7 breast cancer cells and downregulate fatty acid synthase to initiate mitochondrial apoptosis." (PMID 38068849, 2023). "Inhibition of FASN promotes an increase in the NADPH/NADP+ ratio in breast cancer cells; the redox imbalance leads to the activation of stress-related proapoptotic kinases such as JNK and p38 MAPK as well as energy-sensing AMP-activated protein kinase (AMPK)." (PMID 38060103, 2023). "As regard to lipid metabolism, TVB-2640, a specific FASN inhibitor targeting fatty acid (FA) synthesis, is proved to suppress proliferation and proceeded into a phase II breast cancer trial." (PMID 36967443, 2023). "Targeting elevated FASN inhibits cancer cell growth in HER2-positive breast cancer and glioma stem cells." (PMID 37444561, 2023). "Inhibiting FASN signaling induces cell cycle arrest and reduced proliferation of breast cancer cells." (PMID 36674685, 2023). "FASN can directly promote the invasion and metastasis of breast cancer cells by mediating the synthesis of fatty acids." (PMID 37853415, 2023). "In line with this notion, resveratrol was shown to down-regulate FASN in Her2-overexpressing breast cancer." (PMID 38001865, 2023). "HIF1α is also capable of indirectly inducing FASN expression by activating sterol regulatory element binding protein 1 (SREBP1) in breast cancer cells." (PMID 37627128, 2023). "The expression of Hepatitis B X-interacting protein (HBXIP) in clinical breast cancer tissues positively correlates with the expression of FASN, contributing to abnormal lipid metabolism and the growth of cancer cells." (PMID 36969840, 2023). "A meta-analysis was conducted to investigate the role of FASN in breast cancer development and its potential prognostic significance." (PMID 37124526, 2023). "The combined inhibition of fatty acid synthase (FASN) and PI3Kα triggers a synergistic anti-tumor effect in 4T1 breast cancer cells, further reinforcing the need to use isoform-specific PI3K inhibitors in combination with other targeted therapies in cancer." (PMID 36765741, 2023). "In particular, HIF1 can induce the expression of the fatty acid synthase gene (FASN) in breast cancer lines or of acyl-CoA synthetase 2 (ACS2), synthesizing the formation of acetyl-CoA from cytoplasmic acetate." (PMID 37627128, 2023). "Inhibition of FASN can suppress breast cancer growth in the brain, highlighting its potential as a therapeutic target for metastasis in breast cancer." (PMID 37700339, 2023). "FASN expression differs significantly among subtypes with highest in HER2-overexpress breast cancers and lowest in triple-negative breast cancers." (PMID 37124526, 2023). "Inhibiting FASN in cell lines of several breast cancer subtypes have effectively re-sensitized the cells to treatment with conventional chemotherapies paclitaxel, Adriamycin, 5-FU, and vinorelbine." (PMID 37779896, 2023). "In contrast to original breast cancers that had metastasized to other places, a recent study indicated that FASN was more significantly expressed in breast tumors that had spread to the brain." (PMID 37124526, 2023). "The link between FASN expression and the clinicopathological characteristics of breast cancer was examined by five studies." (PMID 37124526, 2023). "In this study, we explored the effect of OST on breast cancer 4T1 cells in the mTOR/SREBP1/FASN signaling pathway." (PMID 36674685, 2023).
breast cancer (continued). "In particular, fatty acid synthase is highly expressed in breast cancer, and has been used as a predictor of decreased tumour-free survival and is associated with the risk of recurrence in breast cancer." (PMID 37108548, 2023). "In another study, Yang and colleagues developed nanoparticles carrying curcumin, which efficiently targeted both PKM2 and FASN and attenuated energy metabolism in breast cancer cell models." (PMID 38001865, 2023). "The fatty acids synthesized by FASN not only provide energy, but also participate in signal transduction in the cellular membrane of breast cancer cells." (PMID 37124526, 2023). "Cancer cells are sensitive to sterols, and the expression of cholesterol and fatty acid biosynthesis genes (SREBF1/2, stearoyl-CoA desaturase (SCD), FASN) was inhibited by 25-HC in cancer cells, such as glioma, breast cancer, and prostate cancer cells." (PMID 36969840, 2023). "Five variants were in genes which have been reported to be associated with breast cancer risk in at least 50 manuscripts in PubMed (DST, CHEK2, FASN, TNN, and PMS2)." (PMID 38136396, 2023). "Inhibiting the expression of FASN in breast cancer cells can reverse the significantly up-regulated fatty acid synthesis." (PMID 37120513, 2023). "Only 14 of these studies investigated the connection between FASN and the prognosis for breast cancer." (PMID 37124526, 2023). "The other top 10 keywords were “expression”, “breast cancer”, “metabolism”, “lipid metabolism”, “fatty-acid synthase”, “growth”, “cancer”, and “cells”." (PMID 37179822, 2023). "Aberrant expression of fatty acid synthase (FASN) was demonstrated in various tumors including breast cancer." (PMID 37124526, 2023). "Third, this investigation examined the relationship between breast cancer patients’ clinicopathological characteristics and FASN expression and found that FASN expression was related to tumor size and HER2 positivity." (PMID 37124526, 2023). "Overexpression of FASN in breast cancer cells promotes their survival and proliferation via the hyperactivation of HER1/2 receptors." (PMID 36934087, 2023). "FASN activity was also found to be crucial for survival of taxane-resistant HER2-over-expressing breast cancer cells." (PMID 37779896, 2023). "Fatty acid synthase (FAS) is a target of breast cancer treatment due to its overexpression in human breast cancer cells." (PMID 37187523, 2023). "Other breast cancer researchers have shown that CRISPR/Cas9 mediated knockout of the FASN gene, which is involved in estrogen receptor signaling, can reduce the proliferation and migration of breast cancer cells." (PMID 36980699, 2023). "Further, overexpression of FASN in mammary epithelial cells drives neoplastic transformation and has been shown to be important to the carcinogenesis of breast cancer." (PMID 38069382, 2023). "FASN is overexpressed in breast cancer stem cells (BCSC), promotes stemness, and is hyperactivated in stemness-enriched samples." (PMID 36934087, 2023). "This revealed synergism of the FASN inhibitor cerulean with docetaxel in HER2 over-expressing breast cancer cell line models." (PMID 37779896, 2023). "The findings presented in this study have identified GART as a new metabolic target that can be used to hinder the growth of breast cancer cells, alongside other targets such as FASN, acid ceramidase, and DHFR." (PMID 37143728, 2023). "From a pathological point of view, the implication of FASN in tumorigenesis was first identified in human breast carcinoma cells in 1994." (PMID 36934087, 2023). "Increased synthesis of fatty acids is achieved by augmented FAS expression by the FASN gene, which is notably overexpressed in breast cancer." (PMID 35053485, 2022). "In trastuzumab-resistant HER2-positive breast cancer cells, overexpression of FASN was facilitated by Pin1 via regulating EGF signaling pathway to activate the sterol regulatory element-binding protein-1c (SREBP1c) promoter." (PMID 35646898, 2022).